STAT3 (signal transducer and activator of transcription 3)
Diseases named in the same sentence as STAT3 in open-access papers (continued):
Sharing a sentence is not in itself a finding about the gene and the disease.
psoriasis (continued). "Our findings indicate terminal differentiation in granular keratinocytes and incomplete squamous corneocyte formation in IL-17 treated STAT3 mice, resulting in characteristic psoriasis lesions." (PMID 37465147, 2023). "JAK2/STAT3 has recently been recognized as a key inflammatory pathway in the development and pathogenesis of psoriasis." (PMID 38007430, 2023). "It was stated that LUT-7G blocked the STAT3 pathway both in vitro and in vivo in a murine psoriasis model." (PMID 37958980, 2023). "The DEGs between IL-17A treated STAT3 mice and WT mice were highly consistent with those observed in psoriasis patients, including S100A8, S100A9, Sprr2, and LCE." (PMID 37465147, 2023). "A research on psoriasis pathogenesis revealed that STAT1 directly antagonized STAT3 and repressed IL-22 expression." (PMID 37391858, 2023). "Other studies have found that total protein and phosphorylated STAT3 levels are significantly higher in psoriatic lesions than in the normal skin, and high expression of active STAT3 can lead to typical psoriasis-like symptoms in mice." (PMID 36835162, 2023). "STAT3 mediates the signal of most cytokines that are involved in psoriasis pathogenesis, including the IL-23/IL-17/IL-22 axis." (PMID 37762217, 2023). "A significant decrease in SIRT1 and, conversely, an increase in STAT3 were demonstrated in a mouse model of psoriasis compared with healthy mice." (PMID 37445960, 2023). "Activation of SIRT1 counteracts oxidative-stress-induced damage and restores redox balance by inhibiting the MAPK, NF-κB and STAT3 pathways, thereby alleviating the course of psoriasis." (PMID 37445960, 2023). "Transgenic mice overexpressing a constitutively active form of STAT3 in basal keratinocytes (K5.Stat3C) develop a mild, psoriasis‐like phenotype that aggravates in response to wounding or 12‐O‐tetradecanoylphorbol‐13‐acetate (TPA) treatment." (PMID 37226685, 2023). "STAT3 inhibition is key to alleviating psoriasis symptoms, and studies have shown that ERK signalling affects STAT3 expression." (PMID 37445960, 2023). "Elevation of TRIM27 level and activation of IL-6/STAT3 signalling pathway were found in an in vivo psoriasis-like inflammation model, whereas inhibition m6A methylation strongly alleviated the inflammation." (PMID 38146129, 2023). "Similar data indicate that rosmarinic acid reduces IL-23 production, suppresses Th17-dominated inflammation, and down-regulates the Jak2/Stat3 signal pathway, suppressing psoriasis-like skin inflammation in vivo and in vitro." (PMID 37663384, 2023). "STAT3 plays an important role in the development of psoriasis, excessive keratinocyte proliferation is directly related to the development of the disease, and STAT3 can promote cell proliferation and differentiation." (PMID 37445960, 2023). "On the other hand, in the case of STAT3, previous research reports have been made stating it to be a mediating pathway of alleviating skin inflammatory damage of psoriasis through the anti-inflammatory and antioxidant activities of natural products." (PMID 37631075, 2023). "Signal transducers and activators of transcription 3 (STAT3) play a crucial role in linking activated keratinocytes and immunocytes during psoriasis development." (PMID 37465147, 2023). "In summary, our data demonstrated that BAC alleviated progression through inhibiting HaCaT cell proliferation, reducing the release of inflammatory cytokines and accumulation of Th17 cells via STAT3 pathways to improving psoriasis." (PMID 37298949, 2023). "In summary, our data demonstrated that BAC alleviated progression by inhibiting HaCaT cell proliferation, reducing the release of inflammatory cytokines and accumulation of Th17 cells via the STAT3 pathway to improve psoriasis." (PMID 37298949, 2023). "Here, we established a psoriasis mouse model by intradermal injection of recombinant IL-17A into the dorsal skin of STAT3 transgenic mice." (PMID 37465147, 2023).
psoriasis (continued). "Recent studies have shown that epidermal hyperproliferation, differentiation, and inflammatory responses depend on STAT3 activation in the IMQ-mediated psoriasis model." (PMID 36838711, 2023). "The IHC analysis indicated that the AKT/STAT3 signaling pathway is activated in both human psoriatic lesions and mouse psoriasis‐like skin." (PMID 38156380, 2023). "The high expression of LMO4 was consistent with high levels of IL‐6, p‐AKT, and p‐STAT3 in the lesions of both psoriasis patients and imiquimod‐induced psoriasis‐like mice." (PMID 38156380, 2023). "To investigate this possibility, we activated STAT3 in vitro to mimic the chronic inflammation model of psoriasis." (PMID 36838711, 2023). "It has been reported that sunitinib reduces imiquimod-induced psoriasis-like inflammation by inhibiting p-STAT3." (PMID 37298949, 2023). "In immune cells activated by chronic inflammation, the transcription of STAT1 and STAT3 promotes cytokine secretion during psoriasis." (PMID 36838711, 2023). "Studies have found that mice with high expression of the STAT3 pathway can spontaneously develop psoriasis-like skin lesions." (PMID 35265149, 2022). "In summary, PCs relieve psoriasis-like symptoms, inhibiting the inflammatory response and attenuating oxidative damage, probably via inactivation of STAT3/PI3K and activation of HO-1." (PMID 35720176, 2022). "Consistently, our study manifested that the expression and phosphorylation levels of STAT3 were suppressed by triptolide both in vivo and in vitro, which indicated that psoriasis development is inhibited by triptolide through suppression of STAT3." (PMID 36474621, 2022). "CDK4/6-mediated phosphorylation of EZH2 at Thr345 enhances STAT3 methylation in keratinocytes, which activates STAT3 to induce the expression of a key proinflammatory transcription factor, IκBζ in psoriasis." (PMID 35659740, 2022). "The discovery of the central role of STAT3 signaling in psoriasis pathogenesis has promoted the development of new drugs such as JAK inhibitors." (PMID 35874668, 2022). "Mechanistic study indicated that the protective role of PNU-282987 in psoriasis was attributed to the suppression of STAT3 and NF-κB signal pathways." (PMID 35351863, 2022). "Because STAT3 has emerged as a key role in the development and pathogenesis of psoriasis, and K5.Stat3C mice has spontaneously developed psoriasis-like lesions." (PMID 36419191, 2022). "It was proposed that increased miR-203 expression in psoriasis lesions is correlated with diminished cytokine-signaling 3 (SOCS3) suppression and a resulting rise in the transcription factor (STAT-3), which is closely linked to the development of psoriasis." (PMID 36341243, 2022). "This study provides direct experimental evidence that PNU-282987 can reduce psoriatic inflammation by inhibiting the activation of the STAT3 and NF-κB signal pathways, thereby inhibiting Th17-related immune responses in psoriasis." (PMID 35351863, 2022). "The transgenic mouse model overexpressing STAT3 in keratinocytes led to the spontaneous development of psoriasis-like lesions with similar cytokine profiles as those of human psoriatic plaques." (PMID 35075118, 2022). "IL-6 and IL-8 have been proven to play important roles in psoriasis, and both of them can initiate STAT3 and JNK MAPK pathway, thus involving in regulating cell inflammation and proliferation of keratinocytes." (PMID 35586566, 2022). "Aberrant STAT3 activation was observed in main cell types involved in the pathogenesis of psoriasis including Th17 cells, γδ T-cells, and keratinocytes." (PMID 35116069, 2022). "In the pathogenesis of psoriasis, the STAT3 pathway was involved in regulating the secretion of Th17 cytokines." (PMID 35265149, 2022). "All these findings suggested that triptolide inhibited the phosphorylation of STAT3 via elevating miR-204-5p and thus repressing Th17 response and psoriasis development." (PMID 36474621, 2022).
psoriasis (continued). "Compound 1 also inhibited the phosphorylation of STAT3, which regulates the expression of cytokines and chemokine in the psoriasis condition." (PMID 36015080, 2022). "EZH2 methylates and enhances STAT3 phosphorylation in keratinocytes and promotes inflammation in the psoriasis model." (PMID 35795677, 2022). "The results showed that the protein expression of p‐JAK/JAK and p‐STAT3/STAT3 in Model group was significantly enhanced compared with Control group (p < .05), indicating that psoriasis modeling by IMQ activated JAK/STAT3 signaling pathway." (PMID 36444619, 2022). "On the other hand, substantial evidence has shown that STAT3 is crucial in the development and pathogenesis of psoriasis." (PMID 35860030, 2022). "To investigate the role of miR-204-5p and STAT3 in triptolide-mediated psoriasis in vivo, we examined the expression of miR-204-5p and STAT3 in healthy skin tissues and triptolide-treated psoriatic lesion skin tissues of mouse models." (PMID 36474621, 2022). "Conclusively, our results manifested that triptolide inhibited Th17 response by upregulating miR-204-5p and suppressing STAT3 phosphorylation in psoriasis." (PMID 36474621, 2022). "IL-6 and IL-22 are Th17-related cytokines that activate STAT3 synergistically and contribute to the pathological development of psoriasis." (PMID 35351863, 2022). "Triptolide inhibits STAT3 phosphorylation via upregulating miR-204-5p and thus suppressing Th17 response in psoriasis." (PMID 36474621, 2022). "Inhibition of STAT3 activation has shown efficacy in treating psoriasis, both in preclinical and clinical studies." (PMID 36555642, 2022). "PAR1 signaling stimulates the expression of various growth factors in macrophages and is also involved in psoriasis via the activation of STAT3, which can stimulate TNF-α, IL-23, and IL-17 production." (PMID 36552865, 2022). "EZH2 inhibition effectively attenuates psoriasis-like skin lesions by suppressing STAT3-mediated IκBζ expression." (PMID 35795677, 2022). "STAT3 has recently emerged as a key player in the development and pathogenesis of psoriasis and psoriasis-like inflammatory conditions." (PMID 34679602, 2021). "The model proposes the inhibition of STAT3 as well as the inhibition of other entities that control many inflammatory genes that sustain the inflammatory cycle of psoriasis and have been previously studied as potential drug targets." (PMID 34877506, 2021). "On the other hand, upon stimulation with IL-22 the activated keratinocytes respond through STAT3 up-regulation and changes in their differentiation profile toward hyper-keratinization and hyperproliferation as hallmarks of psoriasis." (PMID 33986690, 2021). "Cytokines such as IFN-γ, IL-17A or IL-22 bind to cell surface receptors and the signal transduction occurs through JAKs, which in turn promotes STAT1 and/or STAT3 phosphorylation and activation in psoriasis." (PMID 33986690, 2021). "Growing evidence has shown that both STAT3 and NF-κB were activated and overexpressed in both psoriasis patients and psoriasis-like mice." (PMID 35153762, 2021). "In psoriasis, in addition to the activation of STAT3 in keratinocytes, STAT3 is activated by various stimuli in Th17 cells, which play an important role in the pathogenesis of psoriasis." (PMID 34679602, 2021). "In psoriasis, activation of NF-κB and STAT3 in keratinocytes results in the production of pro-inflammatory cytokines such as IL-6 and IL-8." (PMID 34641358, 2021). "The importance of STAT3 in the pathogenesis of psoriasis was demonstrated by the conditional STAT3 overexpression in mouse skin, leading to epidermal hyperplasia and the development of a psoriasis-like phenotype." (PMID 33801280, 2021). "STAT3 activation in keratinocytes is regarded as the main effector producing cytokines, which in turn leads to the positive feedback loop of psoriasis." (PMID 34054833, 2021).
psoriasis (continued). "In this study, we investigated the rate of active STAT3 tumors in patients with psoriasis compared to that in patients with eczema." (PMID 34679602, 2021). "The mRNA expression of STAT3 was up-regulated while SIRT1 was down-regulated in human psoriasis skin tissues than normal skin tissues via RT-PCR detection." (PMID 34044769, 2021). "Topical treatment with STA-21, a STAT3 inhibitor, improved human psoriatic skin lesions as well as psoriasis-like dermatitis in K5.Stat3C transgenic mice, indicating a promising role of this agent in the treatment of psoriasis." (PMID 34501328, 2021). "Tregs are likely suppressed in psoriasis because of the pro-inflammatory cytokine milieu, particularly IL-6 and IL-21, which operate through the adaptor molecule signal transducer and activator of transcription 3 (STAT3)." (PMID 34639182, 2021). "Stattic V, another STAT3 inhibitor, restored the suppressive function of Tregs in patients with psoriasis." (PMID 34501328, 2021). "A previous report indicated that sunitinib reduces imiquimod-induced psoriasis-like inflammation by inhibiting p-STAT3." (PMID 34044769, 2021). "IL17-A is known as a key effector in psoriasis, and the phosphorylation of STAT3 contained with its expression was increased in psoriasis lesions." (PMID 34445513, 2021). "The activation of STAT3 in keratinocytes partly stimulates the activation of Langerhans cells through IL-1α, and their presence is vital to the pathogenesis of psoriasis through the production of IL-23." (PMID 34044769, 2021). "In this investigation, we evaluated the anti-psoriatic effect in IMQ-induced psoriasis-like mice model and explored the mechanism of DB through its regulation on IL-23/TH-17 axis, and NF-κB, STAT3, MAPK signaling pathways." (PMID 34925011, 2021). "In contrast, narrowband UVB irradiation had a suppressive effect on psoriasis by downregulating the expression of keratin 17 through inhibition of STAT3 activation, depending on the irradiation dose." (PMID 34679602, 2021). "Since activation of STAT3 plays a critical role in psoriasis, we investigated the effect of curcumol on STAT3 signaling in M5-stimulated NHEK cells." (PMID 34314383, 2021). "Regarding its function in psoriasis, STAT3 activation in psoriatic keratinocytes occurs by IL-17, IL-19, IL-21, IL-22, visfatin, and IL-36." (PMID 34679602, 2021). "Overall, these results indicated that PPPs ameliorated the symptoms of psoriasis through inhibition of the inflammatory cytokines by suppressing the NF-κB and STAT3 signaling pathways and improved skin barrier protection via enhancing AQP3 and FLG." (PMID 35153762, 2021). "STAT3 mediates the signal of most cytokines in pathogenesis of psoriasis, including IL-23, IL-17A, IL-22." (PMID 34925011, 2021). "Instead, STAT3 activation is intricately regulated by each disorder or cellular microenvironment in both cancer and psoriasis." (PMID 34679602, 2021). "Previous evidence has shown that both the NF-κB and STAT3 signaling pathways were overexpressed and activated in skin tissues with psoriasis." (PMID 35153762, 2021). "Overexpression of CHUK, IKBKB, NFKBIA, NFKB1, JAK2, STAT1 and STAT3, as inflammation related factors, was detected in the psoriasis model group." (PMID 34834106, 2021). "Recently, a few researchers reported that the expression and activation of STAT3 are increased in epidermal keratinocytes as well as in Th17 cells of psoriasis lesions." (PMID 34445513, 2021). "Treatment of human keratinocytes with IL17A, TNF-α and IL-22 upregulates KRT17 by the transcription factor STAT3 that is constitutively phosphorylated in psoriasis." (PMID 33801280, 2021). "Previous studies have indicated an important role of STAT3 in the development and pathogenesis of psoriasis." (PMID 34314383, 2021).
psoriasis (continued). "The immunohistochemistry results showed that compared with the skin cells of normal subjects, the skin cells of patients with psoriasis showed substantially increased STAT3 expression and substantially decreased SIRT1 expression." (PMID 34044769, 2021). "Strikingly, the protein levels of ERBB4, as well as STAT3 and NF-κB, were significantly upregulated in lesional skin samples from psoriasis patients." (PMID 34667159, 2021). "hsa-miRNA4516 was reported to be involved in STAT3 (MIM 102582) regulation and also associated with psoriasis." (PMID 34452458, 2021). "STAT3 has recently been revealed to play a role in the development and pathogenesis of psoriasis and psoriatic-inflammatory conditions." (PMID 34445513, 2021). "It has been reported that the STAT3 protein plays a key role in the occurrence and development of psoriasis." (PMID 34202301, 2021). "IL-6 and IL-22, which are potent STAT3 activators, are known for their synergistic action with IL-17A in the pathogenesis of psoriasis." (PMID 34445513, 2021). "Since then, STAT3 hyperactivation has been reported in the cell types involved in psoriasis, including Th17 cells and keratinocytes." (PMID 34679602, 2021). "Previous studies suggested that the activation of MAPK and STAT3 signaling pathways promoted the development of psoriasis." (PMID 33149756, 2020). "Signal transducer and transcription activation (STAT3) has recently emerged as a key player in the pathogenesis of psoriasis and psoriasis-like inflammatory conditions." (PMID 32811699, 2020). "In psoriatic patients, STAT3 is activated in lesional keratinocytes, which can lead to the development of regenerative epidermal phenotype observed in psoriasis." (PMID 32671018, 2020). "In accordance, biological or natural molecules such as indirubin and its derivatives useful for inactivating STAT3 exhibit therapeutic potential for psoriasis." (PMID 32070069, 2020). "Another study had demonstrated that STAT3 pathway is believed to play a role in the pathogenesis of psoriasis where STAT3 is activated by IL-22 and result in the increased expression of β-defensin 2/3." (PMID 32848730, 2020). "In conclusion, GA ameliorated the symptoms of psoriasis, at least in part, through inhibition of inflammatory cytokines and STAT3/mTOR signaling and activation of Tregs in both lymph nodes and spleens." (PMID 32908937, 2020). "STAT3 is crucial for the induction of inflammation and keratinocyte proliferation in psoriatic skin lesions; thus, STAT3 is considered a potent target for psoriasis therapy." (PMID 33149756, 2020). "Inhibiting the activation of STAT3 using a topical inhibitor affected not only the animal model of psoriasis but also patients with actual psoriasis." (PMID 33149756, 2020). "In particular, expression of constitutively active STAT3 (STAT3C) in keratinocytes leads to the spontaneous development of psoriasis in transgenic mice." (PMID 30894513, 2019). "Considerably increased in psoriasis, IL-23 is a pro-inflammatory cytokine attributed to regulate Treg cells via STAT3 pathway activation, thus disturbing Treg cell function, recognized as a hallmark of psoriasis." (PMID 30744173, 2019). "In this study, MEDD reduced the numbers of inflammatory cells and IL-17 by decreasing STAT1 and STAT3 in IMQ-induced psoriasis." (PMID 31791315, 2019). "This review, overall, indicates that psoriasis is a common dermatitis associated with oxidative stress mediated by MAPK, NF-κB, and STAT3 signaling cascade." (PMID 31495284, 2019). "While IL-6R activates the Akt and MAPK pathways in dermal fibroblasts, STAT3 is known to be activated in keratinocytes, specifically at the wound edge, during healing as well as during skin pathologies such as psoriasis." (PMID 31073533, 2019). "In summary, activation of SIRT1 can counteract the damage caused by oxidative stress by inhibiting the MAPK, NF-κB, and STAT3 pathways, leading to the alleviation of the pathological injury in psoriasis." (PMID 31495284, 2019).